PON1 (paraoxonase 1)
Diseases named in the same sentence as PON1 in open-access papers (continued):
Sharing a sentence is not in itself a finding about the gene and the disease.
tumor (continued). "The results seem to be valid and justified by the presumed role of PON1 as an antioxidant factor, as tumor growth and metastasis are closely related to oxidative stress and inflammatory processes." (PMID 36290747, 2022). "The vaccine somewhat restored the deterioration of the biochemical parameters (LDH, GOT, GPT, MDA, NO, and PON-1) in the tumor-bearing mice." (PMID 36308603, 2022). "ROC analyses revealed that PON1 concentration allowed identification of the patients with two affected positive nodes (including the presence of tumour cells in 4 or more regional lymph nodes), with an AUC value of 0.755 (sensitivity = 87%, specificity = 54%)." (PMID 33886674, 2021). "Some studies investigated the relationships between serum PON1 activities and tumor stage, and reported that local progress of the disease was associated with lower enzyme activities in patients with ovarian and gastroesophageal cancers." (PMID 34356595, 2021). "In conclusion, PON1 can serve as a diagnostic biomarker for CRC and raise the sensitivity and specificity when incorporated with traditional tumor biomarkers." (PMID 33046970, 2020). "PON1 in the RCC tumour tissues from 15 RCC patients was highly methylated which had the clinicopathological significance." (PMID 31400051, 2019). "We found that PON1 downregulation in HCC suggests worse tumor differentiation, higher recurrence rate, stronger invasiveness, and poorer outcomes." (PMID 30477582, 2018). "Then we further elaborated the consequence of PON1 regulation in LC cells and tumor xenografts and that the exploitation of its antioxidative function can impact tumorigenesis and escape from cell death." (PMID 28467805, 2017). "Statistical significance (P-value) of the differences between serum PON1 activities and concentrations pre- and post-radiotherapy vs. the selected tumor and toxicological variables." (PMID 29176871, 2017). "Condensed structure and greater tumor masses were observed in both PON1-overexpressing tumors while smaller size tumors with more spatial mass of cells were observed in PON1-knockdown A549 tumors." (PMID 28467805, 2017). "In this study, we identified notable LC cell-autonomous function for PON1 providing evidence of regulating the response mechanism of LC cells to oxidative stress with functional consequences in LC tumor physiology, metastatic potential, and cell death." (PMID 28467805, 2017). "The functional data imply that exploitation of the antioxidative function of PON1 is consequential in driving LC pathogenesis at the cell-autonomous mechanistic level with consequences on tumor growth." (PMID 28467805, 2017). "We present evidence for PON1 having anti-apoptotic and anti-oxidative features in LC cells eliciting tumor growth." (PMID 28467805, 2017). "As to GSTP1 and PON1 192 polymorphisms, the mutant Val and R alleles, respectively, were associated with a decreased risk of developing BC, while polymorphisms in PON1 55 and GLO1 were associated with an increased risk of this neoplasia." (PMID 19379515, 2009). "This suggested that high expression of CDC20, LPCAT1, and SPP1, as well as low expression of PON1, may affect the immune escape and cell metabolism of tumor cells, reducing TACE treatment sensitivity." (PMID 40404896, 2025). "The finding of decreased PON-1 activity in dogs with high-grade MCTs, according to both the Kiupel and Patnaik grading systems, highlights the potential role of oxidative stress in tumor progression, as well as the potential prognostic role of PON-1 levels in canine MCTs." (PMID 39765802, 2024). "Female HCC patients with low PON1 expression had a higher degree of tumor malignancy." (PMID 39594433, 2024). "The mean values of PON-1 were significantly higher in the low-grade neoplasms." (PMID 39765802, 2024).
tumor (continued). "PON1 not only can reduce the inhibition of leukocyte adhesion and chronic inflammation of vascular walls (especially macrophages and monocytes) but also participate in cell cholesterol synthesis and result in tumor invasion/metastasis." (PMID 36263042, 2022). "Interestingly, in our study, direct correlations between branched-chain amino acid levels and PON1 activity were observed, suggesting that patients with more metabolically active tumours have lower enzyme activities, perhaps due to increased oxidative stress." (PMID 33886674, 2021). "Compared with normal tissues, PON1 showed obvious hypermethylation in KIRP tumour tissues." (PMID 31400051, 2019). "Collectively, 5‐Aza‐dC and TSA could synergize the effect of inhibition of sunitinib‐resistant RCC tumour growth by inducing PON1 re‐expressed." (PMID 31400051, 2019). "The vivo experiment indicated that demethylated PON1 suppressed the growth of tumour." (PMID 31400051, 2019). "There is a real possibility that PON1 participates in this phenomenon, and the reduced serum concentrations of this protein are a reflection of an inhibited secretion tending towards an increase in the intra-tumor levels of this enzyme." (PMID 29176871, 2017). "Molecularly, PON1 is released by a high-affinity desorption mechanism and malignancies take advantage of its regulating effects on systemic oxidative-stress to affect tumor development with specific actions in the elimination of lipid-soluble radicals from lipid peroxidation." (PMID 28467805, 2017). "PON1 Q192R and L55M genotypes were then analyzed according to tumor stage." (PMID 19379515, 2009). "Similarly, metastases in lymph nodes and portal vein tumor thrombus also presented their significant expressional variation of PON1 and NR0B1 in the hepatocyte subclusters, which might be associated with their different invasion capacity." (PMID 38374122, 2024). "Therefore, PON1 downregulation might be increased by complicated internal mechanisms related to cell division, proliferation, and migration, which could also explain why the expression of PON1 was related to tumor recurrence and clinical outcomes." (PMID 30477582, 2018). "Markers such as chemerin, TSP-1, PON-1, resistin, and MPO correlate with tumour burden and disease activity, while adiponectin and TSP-1 are linked to treatment response." (PMID 41303900, 2025). "HDL anchors several enzymes in its structure, particularly paraoxonase (PON-1), which acts in the hydrolysis of lipid peroxides, minimizing LDL oxidation and the consequent supply of cholesterol and oxysterols to tumor cells." (PMID 36969000, 2023). "The results showed the expression level of PON1, MATN3, and SERPINE1 were increased in the tumor tissues." (PMID 35372408, 2022). "The tumor samples of the TCGA displayed undetectable levels of APOA5 and PON1, as these proteins are found at the systemic level." (PMID 34439311, 2021). "In the present study, PON1, MDA, and PON3 enzyme activities were investigated one month after surgical tumor excision." (PMID 32549522, 2020). "Based on a density plot of PON1 expression, we clearly observed that low PON1 expression in HCC was correlated with stronger invasiveness and metastasis, including tumor T stage, AJCC tumor stage, tumor differentiation and vascular invasion." (PMID 30477582, 2018). "A prognostic nomogram was established between PON1 and several significant clinical factors, including age, sex, vascular invasion, Child–Pugh classification, AJCC staging rules, and tumor differentiation." (PMID 30477582, 2018). "The C-index of the PON1-related nomogram was 0.714, thus indicating a more effective predictive performance than the 7th American Joint Committee on Cancer (AJCC) tumor stage (0.534), AJCC T stage (0.565), or alpha-fetoprotein (0.488)." (PMID 30477582, 2018). "Strong immunoreactivity of ESR1, APOA1, IGF1, and PON1 was observed in normal tissues, whereas weak or no staining was observed in tumor tissues." (PMID 40317014, 2025).
tumor (continued). "Similarly, the highest expression of C2orf27A and IGF2R was found at tumor grade 3, and the lowest expression of CFB and PON1 was found at grade 4." (PMID 33495404, 2021). "According to P values, the levels of PON1 were not obviously correlated with age, T classification, N classification, metastasis, clinical stage and tumor location in CRC patients." (PMID 33046970, 2020). "Even though the expression of PON1 is negatively correlated with tumor recurrence, metastasis, and invasion, we did not define it as a tumor suppressor." (PMID 30477582, 2018). "For PON1, in contrast of its positive expression in hepatocyte subclusters of normal livers, metastatic lymph nodes, and primary tumors, its negative expression was shown in portal vein tumor thrombus." (PMID 38374122, 2024). "The lack of correlation between PON-1 and metastasis or IHC markers suggests that oxidative stress as measured by PON-1 may be influenced by tumor biology in a manner independent of these commonly assessed factors." (PMID 39765802, 2024). "Interestingly, the lower PON1 concentration was observed in patients with tumour recurrence compared to patients without tumour recurrence." (PMID 33923108, 2021). "Moreover, a relationship between PON1 and clinical data was reported with lower PON1 concentration in patients with tumor recurrence with respect to patients without tumor recurrence." (PMID 31191796, 2019). "The results of this study suggest that while PON-1 may be an important marker of oxidative stress in high-grade MCTs, other oxidative and lipid metabolism analytes do not appear to be of clinical importance in tumor progression or prognosis." (PMID 39765802, 2024). "In this study, we investigated the differences in gene expression between normal tissues and tumor tissues, as well as TACE response and non-response groups, and intersected them with MRGs, successfully identifying four key genes (CDC20, LPCAT1, PON1, and SPP1)." (PMID 40404896, 2025).
infection (27 papers, 2012 to 2026). The state of being infected such as from the introduction of a foreign agent such as serum, vaccine, antigenic substance or organism. "Interference with quorum sensing by metabolism of acyl-HSLhomoserine lactone by PON1 has also been implicated in resistance to infection with the pathogenic bacterium Pseudomonas aeruginosa." (PMID 38887979, 2024). "The mechanism by which hepatic PON1 mRNA is down-regulated during N. brasiliensis infection in rats is induction by various pro-inflammatory cytokines associated with that infection." (PMID 22824324, 2012). "However, our primary objective was to assess, to the best of our knowledge for the first time, PON1 association with the infection site, pathogen, and the failure of specific organs." (PMID 30886652, 2019). "However, these activities are partially restored in infected animals receiving zinc as an anti-oxidant, indicating that the changes in PON1 are influenced by oxidative stress associated with infection." (PMID 22824324, 2012). "In particular, we identified a unique cholesterol efflux signature, marked by the secretion of APOA1 and PON1, in response to Mycobacterium Tuberculosis, consistent with the metabolic reprogramming that takes place during infection." (PMID 42214753, 2026). "In the experimental infection of dogs with L. infantum, an increase in ferritin (Ft) and a decrease in paraoxonase-1 (PON-1) was observed with a return to pre-infection values following treatment." (PMID 39591291, 2024). "This analysis revealed 36 proteins increased in patients at an early stage of the SARS-CoV-2 infection, including the antioxidant PON1, and four proteins with elevated levels in late infection." (PMID 38672194, 2024). "Another elevated protein in CPs is PON1, which has antioxidant activity through the hydrolysis of lipoperoxides, participating in the innate immune response to infections and oxidative stress." (PMID 38672194, 2024). "Previous LC-MS/MS proteomics studies determined an increase in PON1 levels along the first month of infection, as well as a decrease in severity." (PMID 38672194, 2024). "When infection or inflammation becomes generalised, as in, say, septicaemia or systemic lupus erythematosus PON1 activity has declined." (PMID 36873390, 2023). "The mRNA level of PON1 was downregulated until 2 h post-infection (hpi), suggesting that PON1 downregulation occurs after virus entry." (PMID 35746674, 2022). "Haptoglobin was increased, whereas albumin and PON-1 showed a decrease in experimentally infected cattle, and peaks were detected during the first month post-infection." (PMID 34551803, 2021). "The increase in oxidative stress secondary to infection is likely the most important reason for the large decrease in PON1 activity." (PMID 34205807, 2021). "Within the locus we also identified host genes whose expression increased (Samd9l, Asns, Gpr85, and Tfpi2) or decreased (Pon1, Hepacam2, Tmem106b, and Pppr9a1) 2-fold (P < 0.05) 72 hours after infection with H5N1 IAV in D2, B6 or both mouse strains." (PMID 25418976, 2014). "Infection of mice with C. pneumoniae reduces serum PON1 activity and the anti-inflammatory properties of HDL by repressing gene expression via serum amyloid A elevation." (PMID 22824324, 2012). "Down-regulation of Ephx1 and Pon1 may ensure a certain amount of hydrogen peroxide, a potent antimicrobial agent, is present during pathogen infection; 4) Apoptosis-regulating proteins were significantly modulated." (PMID 23826353, 2013). "Interestingly, the expression of human PON1 in transgenic Drosophila results in increased resistance to infection by Pseudomonas aeruginosa via inactivation of the QS factor N-(3-oxododecanoyl)-L-homoserine lactone (3OC12-HSL) of Pseudomonas." (PMID 22824324, 2012).
infection (continued). "Furthermore, we conducted secondary analyses to verify whether PON-1 and PON-2 polymorphisms and paraoxonase activity are associated with lipid and infection markers in PLWH using different antiretroviral therapies." (PMID 40002395, 2025). "Finally, we wished to know whether there were any difference in serum PON1 values in relation to the days elapsing between the commencement of the infection and the measurement of PON1." (PMID 35883435, 2022). "Paraoxonase-1 (PON1), an esterase with specifically paraoxonase activity, has been proven to be involved in inflammation and infection." (PMID 35746674, 2022). "Haptoglobin, albumin, PON-1 and ADA were identified as the biomarkers that showed changes of higher magnitude in the acute phase of the infection, whereas high total protein and globulin values were found in chronically infected cattle." (PMID 34551803, 2021). "Haptoglobin, albumin, PON-1 and ADA were identified as the most promising biomarkers for the acute phase of the infection." (PMID 34551803, 2021). "The biomarkers associated with an acute infection (Hp, albumin, PON-1 and ADA) are related to previously reported molecular biomarkers in the testicular parenchyma of infected bulls and could help in the diagnosis of early infections and complement IgM detection." (PMID 34551803, 2021). "In humans, PON-1 activity and CCL-2 concentration have an inverse correlation during natural infection and CCL-2 decreases together with the increase of PON-1 and the resolution of naturally occurring septic processes after several days of hospitalisation." (PMID 33148245, 2020). "PON1 activity is significantly reduced in MODS, more so in older patients and in patients with CVI and the abdomen as a site of infection." (PMID 30886652, 2019). "In multivariate analysis, 50% of variability in PON1 activity in patients with MODS was explained by the patients' age, CVI, and abdomen as a site of infection." (PMID 30886652, 2019). "Unlike in previous studies focused on survival, our objective was to determine PON1 activity in critically ill patients with MODS and to put it in the context of the clinical type, ongoing inflammation, invading pathogen, infection site, and specific organ failure." (PMID 30886652, 2019). "A trend towards negative correlation between PON1 activities and markers of inflammation and infection was noted but failed to reach significance." (PMID 24665146, 2014). "This includes a decline in serum levels of Paraoxonase-1 and Arylesterase activities, along with reduced Plasma Free Sulfhydryl Groups and a lower Total Antioxidant Capacity when compared to individuals without infection." (PMID 38559670, 2024). "The decrease in serum PON-1 is indicative of the idea that oxidative stress could be occurring in T. cruzi-seroreactive patients with an active infection that has not been controlled, and therefore suggesting that an anti-T. cruzi treatment should be provided." (PMID 37368717, 2023). "Therefore, we measured arylesterase activity of PON1 in 87 individuals (35 with MODS) and related it to the clinical type, organ failure, infection site, pathogens, and hematological and biochemical indices of inflammation at admission to ICU and during a five-day follow-up." (PMID 30886652, 2019). "However, under porcine reproductive and respiratory syndrome virus (PRRSV) infection, Paraoxonase-1 (PON1) has been found to inhibit the IFN-β pathway to promote PRRSV replication by interacting with PRRSV nonstructural protein 9 (Nsp9), resulting in an expansion of infection and inflammation." (PMID 38124132, 2023).